APOE (apolipoprotein E)
Diseases named in the same sentence as APOE in open-access papers (continued):
Sharing a sentence is not in itself a finding about the gene and the disease.
Stroke (continued). "Thus, we conducted a case-control study of stroke with a distinct CT classification in a Bangladeshi hospital so that we could test the hypothesis that the apoE genetic polymorphism was related to stroke differently according to its subtypes." (PMID 11434425, 2001). "The association of ApoE genotype with stroke risk is well-established, but the relationship between circulating ApoE concentration and stroke has received little attention." (PMID 41541874, 2025). "We examined associations of APOE status (APOE2+ [ε2/ε2, ε2/ε3], APOE3 [ε3/ε3], and APOE4+ [ε4/ε4, ε3/ε4] carriers) with incidence of T2DM, coronary heart disease, stroke, and total CVD events using Cox regression." (PMID 39364911, 2025). "Some key genetic markers associated with stroke are brain-derived neurotrophic factor (BDNF), apolipoprotein E (ApoE, variant ε4), angiotensin-converting enzyme (ACE), and nitric oxide synthase 3 (NOS3)." (PMID 40142325, 2025). "As reported by others, for six proteins we observed opposite directionality of associations for plasma versus CSF protein levels (APOE, EPO, PSMP, PRSS8 and TFPI with WMHs, IL-6 with HIP-PVS, and BT3A2 with stroke)." (PMID 41266628, 2025). "Examples of sample sizes in BDNF and APOE genetic studies on stroke outcome and recovery from 2016 and later." (PMID 40215404, 2025). "Particularly, the increase in ApoE and ApoM 24 and 96 h post-stroke has been related to a worse three-month recovery score, as assessed by the NIHSS score." (PMID 38732018, 2024). "Regarding stroke cases, polymorphisms in some genes such as MTHFR, eNOS, ACE, AGT, ApoE, PON1, PDE4D were associated with a higher risk of ischemic stroke." (PMID 38478535, 2024). "APOE ɛ4-carriers with stroke had lower cognitive function in both cognitive domains, which is in agreement with the previously found synergistic effect of having both AD pathology (accelerated by ɛ4-carriership) and cerebrovascular disease." (PMID 38926747, 2024). "Further research is necessary to better elucidate the relationship between APOE and ACE2 polymorphisms associated with COVID-19 outcomes and stroke risk." (PMID 39109239, 2024). "For memory function, APOE ɛ4/ɛ4 and ɛ3/ɛ4-carriers with stroke performed significantly lower on attention/executive function (p < 0.05)." (PMID 38926747, 2024). "Connexin 43 (CX43), aquaporin 4 (AQP4), and apolipoprotein E (APOE) are generally considered to be astrocyte-derived proteins and are closely associated with pathogenesis of ischemia or stroke." (PMID 39766455, 2024). "PET data from age-, sex-, education-, and apolipoprotein E-matched stroke-free controls within a community-dwelling cohort were used to benchmark amyloid deposition." (PMID 39351012, 2024). "Possible explanations include a disproportionate effect of ApoE-Є4 on survival in women compared to men, a direct effect of ApoE-Є4 on stroke AAO, or chance." (PMID 39286457, 2024). "Our finding that APOE genotype influence stroke outcome and has interaction with modifiable hematology index have clinical implications." (PMID 36640294, 2023). "CSF log(Ng) concentrations also differed significantly between A/T/N groups (p<0.001, F=57.7, DF=5), when using age, sex, APOE ε4 carriership, and stroke as covariates in ANCOVA." (PMID 36869347, 2023). "The CSF log(NfL) concentrations between A/T/N groups differed significantly (p=0.005, F=3.44, DF=5), when using age, sex, APOE ε4 carriership, and stroke as covariates in an ANCOVA." (PMID 36869347, 2023). "We also tried to unveil the linkage of the APOE genotype with the concomitant occurrence of AD and stroke." (PMID 35712342, 2022). "Linear, logistic, and Cox-regression models were used to assess the associations of the APOE polymorphism with CCA-IMT, carotid plaques, incident MI and stroke, respectively." (PMID 35332187, 2022). "In the coming section, we will explore in more detail the latest finding on the role of APOE in Parkinson’s disease and other synucleopathies, stroke, TBI, ALS, or MS." (PMID 36153580, 2022).
Stroke (continued). "ApoE ε4 also disturbs lipid homeostasis in astrocytes and microglia and then leads to blood-brain barrier failure in stroke patients." (PMID 36578446, 2022). "APOE has been shown to reduce neurological defects in stroke rat models by increasing APOE2 receptor cholesterol uptake." (PMID 35432801, 2021). "The investigation among the European population showed the association between the genotypes of the ε2/ε3/ε4 alleles of the APOE gene, encoding apolipoprotein E, and the higher LDL cholesterol levels, which correspond with higher CAD risk and stroke." (PMID 34445769, 2021). "Knockout APOE mice have also been shown to have a higher rate of post-stroke neurological damage than mice with APOE, as well as more engaged affected regions." (PMID 35432801, 2021). "The pathogenesis of VaD is complex and is the result of a variety of cardiovascular or genetic risk factors associated with Apolipoprotein E (APOE), angiotensin I converting enzyme (ACE), paraoxonase 1 (PON1), or presenilin 1 (PSEN1) genes, or due to stroke." (PMID 34938197, 2021). "A recent study also demonstrated the association between the methylation status of the ApoE gene promoter and atherosclerotic cerebral infarction (ACI), a common form of stroke." (PMID 31941075, 2020). "Therefore, screening APOE in several populations is of great importance to assess ethnicity-specific differences in the risk for AD and other pathologies influenced by the APOE genotype, such as stroke, cardiovascular diseases, and other neurodegenerative disorders." (PMID 33375167, 2020). "We found statistically significant differences concerning APOE ε4 and the presence of heart disease, stroke, or delirium." (PMID 32767997, 2020). "Brain ABCA1-deficient (ABCA1-B/-B) mice exhibit decreased WM remodeling as well as dysfunctional neurological outcome after stroke, and intracerebral supplementation of human ApoE or HDL reverses the deficits in ABCA1-B/-B stroke mice." (PMID 32575457, 2020). "Taken together, the present study suggests a therapeutic effect of the ABCA1/ApoE/HDL signaling pathway on WM remodeling in the ischemic brain after demyelination induced by stroke." (PMID 32575457, 2020). "Combination of biomarkers and clinical markers allow us to explore the relationship between inflammation and APOE status, chronic inflammation, sedentary behaviour, stroke recurrence and cognition." (PMID 30477436, 2018). "Presence of APOE ε4 also influenced tau deposition (AT8 immunoreactivity) in the post-stroke cohort, the immunoreactivity being significantly higher in APOE ε4 positive subjects in the subiculum (Mann–Whitney U-Test, p = 0.042)." (PMID 29311794, 2017). "Simultaneously, Genetics as a risk factor for stroke have also been confirmed, and some genetic polymorphisms such as MTHFR, ApoE, P-selectin and interleukin-4 gene have been shown to be associated with the risk of stroke." (PMID 29383136, 2017). "To date, few studies have reported on the association of circulating ApoE concentration with CVD events (i.e., stroke and coronary heart disease [CHD])." (PMID 27755538, 2016). "This study explored the relationships between BDNF and APOE genotype, chronic motor status, and motor improvement following a 14-day protocol of upper-limb stroke therapy." (PMID 27242654, 2016). "We examined the association of circulating ApoE with cardiovascular risk factors in the two population-based studies (ELSA and NPHSII) and the relationship between ApoE concentration and coronary heart disease and stroke in all three studies." (PMID 27755538, 2016). "Knowledge of ApoE genotype also provides valuable information about recovery prognosis after an acute event such as stroke, delirium, or traumatic brain injury (TBI)." (PMID 25071563, 2014). "Minor amounts of ApoE are produced in neurons and microglia under normal conditions, but selective up-regulation of neuronal ApoE can occur under pathological conditions such as stroke and AD." (PMID 23720634, 2013).
Stroke (continued). "BNs have already been successfully applied in association studies, for example to study overt stroke in sickle cell anaemia and to identify the relationships between SNP variations in the human APOE gene and plasma apolipoprotein E levels." (PMID 19208195, 2009). "Specific apolipoprotein E (APOE) alleles are not only a strong risk factor for development of AD, but are also linked to development of CAA and strokes." (PMID 19468344, 2009). "Recent analyses included 203 studies for a period from 1970 to 2007, providing ultimate proof of the significant association between genetic variants of the APOE gene and CAD and stroke." (PMID 22649614, 2009). "Previous studies, such as those examining NINJ2 or APOE polymorphisms, have linked specific alleles with earlier or later stroke presentation—even in the absence of traditional vascular risk factors." (PMID 41324337, 2026). "While ApoE has been associated with CHD and stroke, its relationship with PAD is less clear." (PMID 41465167, 2025). "Investigating the interplay between ApoA-II and other cholesterol transport proteins, such as ApoE, could provide insights into potential compensatory mechanisms in stroke and AD." (PMID 40869228, 2025). "Stratifying by race APOE ε4 allele carriership and excluding those with prevalent stroke (data not shown) didn’t change the findings." (PMID 39877085, 2025). "Circulating ApoE concentration is associated with levels of major circulating lipids and lipoproteins, including total cholesterol, LDL, and HDL and triglycerides, but data on its association with stroke is conflicting." (PMID 41541874, 2025). "The main aim of this exploratory study was to investigate plasma MCP-1 and ApoE concentrations as risk factors for HIV-associated stroke by comparing young PWH with and without ischemic stroke." (PMID 41541874, 2025). "Understanding how these apolipoproteins interact with one another and with other lipid transporters, such as ApoE, may reveal compensatory mechanisms that modulate stroke outcomes and inform future therapeutic strategies." (PMID 40869228, 2025). "In addition to ApoE ε4, several other factors, such as age, BMI, education level, and initial stroke severity, were identified to be significant contributors to the development of PSCI in our study." (PMID 40349252, 2025). "Our findings suggest that, aside from traditional risk factors, the ApoE ε4 allele does not contribute to the risk of PSCI at 3 or 12 months post-stroke." (PMID 40349252, 2025). "APOE ɛ3/ɛ4 and ɛ4/ɛ4-carriers with stroke had lower memory performance (p < 0.05)." (PMID 38926747, 2024). "ApoE concentrations were lower in patients than in controls and remained low 1 year after stroke." (PMID 39746448, 2024). "Some studies have shown that the plaque of AS model in ApoE-/- mice is not easy to rupture, so it is impossible to simulate acute myocardial infarction and stroke caused by plaque rupture in clinic." (PMID 38498570, 2024). "Research also suggests that both apolipoprotein E (ApoE) and methylenetetrahydrofolate reductase (MTHFR) may contribute to an increased risk of major depressive disorder after a stroke." (PMID 39337894, 2024). "Although much is known about how apoE-cholesterol-derived from astrocytes affects the build-up of synaptic circuits and impairment in AD (the latter according to apoE2 < apoE3 < apoE4), a gap of knowledge remains on apoE role on brain synapses following stroke under adverse environments." (PMID 39109239, 2024). "Although APOE-ε4 was previously linked to cardiovascular diseases (including heart attack and stroke), we did not observe a significant direct effect of APOE-ε4 on mortality due to cardiovascular illnesses." (PMID 37434484, 2023). "The reasons why APOE genotype influence stroke outcome remain understudied." (PMID 36640294, 2023). "Odds ratios of APOE ε4 status for unfavorable 3-month stroke outcome." (PMID 36640294, 2023).
Stroke (continued). "ApoE can induce NSCs and neural progenitor cells to differentiate into additional oligodendrocytes and facilitate myelination and oligodendrogenesis after stroke." (PMID 37592237, 2023). "Significantly, two of these same inflammatory polymorphisms in TNFα (-238G>A) and ApoE (ApoE ε2) may increase vascular instability post-treatment, as they are associated with an increased risk of ICH stroke following surgical intervention." (PMID 38001877, 2023). "To evaluate the relationship between APOE isoforms and stroke outcome and to investigate the potential interaction of APOE genotype and inflammation level in patients with AIS, we undertook this retrospective cohort study of AIS and follow-up for 3-month functional outcome." (PMID 36640294, 2023). "Interestingly, the Apolipoprotein E (ApoE) genotype, which encodes for a protein involved in cholesterol metabolism, has been implicated in both ICH stroke and subarachnoid hemorrhage." (PMID 38001877, 2023). "This impact increases in APOE ε4 carriers and may increase infarct size, results in poor recovery after stroke." (PMID 36640294, 2023). "This study aims to determine whether APOE alleles would affect the functional outcome in acute ischemic stroke (AIS) and whether the relationship between inflammation and stroke-related disability varies according to APOE genotypes." (PMID 36640294, 2023). "The APOE genotype influences the age onset of stroke and its severity." (PMID 36153580, 2022). "Stroke was induced via middle cerebral artery electrocoagulation in 8–9-week old mice (young mice), 18 month old mice (aged mice), and in high-fat diet-fed 22-week old ApoE−/− mice (hyperlipidaemic mice)." (PMID 35910379, 2022). "Therefore, we examined the association of different APOE alleles with common carotid artery intima-media thickness (CCA-IMT), carotid plaques, incident myocardial infarction (MI) and stroke." (PMID 35332187, 2022). "Nonetheless, the authors did not observe any association between the APOE alleles and stroke severity." (PMID 36153580, 2022). "Considering that aspiration pneumonia may increase post-stroke mortality, this new role of APOE may be clinically relevant." (PMID 36005151, 2022). "ABCA1/ApoE were reported in many research about their effects in neural restoration after stroke." (PMID 33504361, 2021). "In addition, the toxic effect of alcohol can be influenced by genes; for example, men carrying APOE ε2ε3 have a greater tendency to suffer from strokes than those with ε3ε3 when they have alcohol exposure." (PMID 33551739, 2021). "MCI status at wave 3 and wave 5 (but not wave 4) was significantly associated with APOE ε4 status and history of stroke." (PMID 33480611, 2021). "In addition, two factors affecting memory in women at mid-life had very limited modifiability (APOE e4, stroke)." (PMID 33833259, 2021). "Results were similar in analyses including participants’ cognitive observations after the time of incident stroke, adding glomerular filtration rate and history of myocardial infarction as covariates, and adding APOE ε4 and APOE ε4 × time variables as covariates (eTables 3-5 in the Supplement)." (PMID 33630089, 2021). "However, a previous study suggested that stroke patients with the APOE genotype ε3/ε3 had more symptoms of depression compared to the other genotypes." (PMID 33178131, 2020). "CAD, stroke, and APOE‐ε4 positive were more frequently observed in the cases." (PMID 32864870, 2020). "As exhibited by stroke, vascular dementia, multiple sclerosis, Parkinson’s disease, dementia with Lewy bodies, and so on, there are many other neurological disorders that are affected by the APOE gene or that can interact with the APOE gene." (PMID 30866553, 2019). "Studies have shown that apolipoprotein E (APOE) polymorphism is associated with PSD, APOE rs429358 polymorphism increases the probability of PSD, APOE rs429358-C allele may be post-stroke nerve Functional recovery is harmful." (PMID 30728786, 2018).
Stroke (continued). "Overall, 11 out of 29 (37.9%) post-stroke subjects were APOE ε4 positive." (PMID 29311794, 2017). "Here, we investigated whether BDNF and APOE genotype influence how stroke patients with stable motor function respond to a targeted protocol of upper-limb motor therapy poststroke." (PMID 27242654, 2016). "Other SNPs in genes involved in inflammation (APOE and IL6), oxidative stress (NOS3 and SOD2), and As metabolism (AS3MT, CBS, GSTO1, and MTHFR) showed nominally significant interactions with well-water As for associations with CVD, CHD, or stroke." (PMID 25575156, 2015). "ApoE3-TR and ApoE4-TR mice offer a valuable tool for assessing the contribution of human ApoE isoforms in the outcome of stroke in the context of unhealthy human food intake and old age, thereby increasing the clinical relevance of the research compared with studies using naïve healthy mice." (PMID 23957944, 2013). "For example, polymorphisms of the apolipoprotein E (APOE) and brain-derived neurotrophic factor (BDNF) genes may influence outcome after stroke." (PMID 23750149, 2013). "Old ApoE−/− mice with an elevated expression of AQP4 subjected to stroke might have a worse outcome with a higher degree of edema formation as previously proposed with AQP4 overexpression in transgenic mice." (PMID 22709928, 2012). "Compared to the majority of individuals having the ε3 isoform (gene frequency approximately 0.77), the fewer individuals having the ε2 isoform (gene frequency approximately 0.08) have the highest levels of blood APOE and lower cholesterol levels and protection from cardiovascular disease and stroke." (PMID 21223544, 2011). "A significant interaction was observed between APOE ε4 and stroke (P = 0.001)." (PMID 20576093, 2010). "The interaction between stroke and APOE ε4 remained significant (P = 0.018)." (PMID 20576093, 2010). "On the other hand, ApoE-ε2 appears to promote degenerative changes in the amyloid-laden vessel wall and is a cause of stroke independent of Aβ deposition." (PMID 19468344, 2009). "In a review of 500 papers, a significant and direct association between the APOE and strokes in Asians (Chinese, Japanese, Koreans)---but not in Caucasians---was established." (PMID 22649614, 2009). "This research would not only be relevant to AD, but also to a number of other neurological diseases that may be modulated by apoE such as stroke, multiple sclerosis and traumatic brain injury." (PMID 17430597, 2007). "Overall, each gene studied seemed to have a similar effect in the different populations, with the exception of APOE, which seemed to be associated with stroke in the Asian studies but not in the studies from people of non-European origin." (PMID 17455988, 2007). "Odds ratio* (95% confidence interval) of ApoE genotypes with stroke subtypes." (PMID 11434425, 2001). "Among three cohort studies), the non- detection of any association with apoE genetic polymorphism probably resulted from not taking into consideration heterogeneous pathogenesis in differing stroke subtype." (PMID 11434425, 2001). "The association between apolipoprotein E (apoE) genetic polymorphism and stroke has not been concordant in different racial populations." (PMID 11434425, 2001). "Therefore, we will collect APOE genotypes from stroke patients in the future." (PMID 39949537, 2025). "Notably, genetic factors such as ApoE polymorphisms appear to differentially influence AP risk, demonstrating significant association in younger stroke patients but not elderly populations." (PMID 40529443, 2025). "We hypothesized that APOE ε4 allele may be a predictor for poor functional outcome in patients with AIS, furthermore, APOE ε4 carrier status may modify the previously established relationship between NLR and stroke outcome." (PMID 36640294, 2023).